PRMT5 (protein arginine methyltransferase 5)
Diseases named in the same sentence as PRMT5 in open-access papers (continued):
Sharing a sentence is not in itself a finding about the gene and the disease.
tumor (continued). "A recent report identified that PRMT5 is overexpressed in MCL, and application of PRMT5 specific inhibitor PRT382 was found to reduce tumor burden in an ibrutinib-resistant MCL-PDX mouse model." (PMID 32455989, 2020). "The R205 methylation of YBX1 is important for its interaction with p65, revealing a novel cooperativity between YBX1 and PRMT5 that dynamically modulates NF-κB activity and target gene expression to render a tumor-promoting effect in CRC cells." (PMID 32985589, 2020). "PRMT5 inhibition and knockdown have also been shown to restore key regulatory pathways that are involved in cell growth, survival, migration, and tumor suppressor activity." (PMID 32731506, 2020). "MTAP-deficient tumor cells accumulate high levels of MTA leading to a reduced PRMT5 activity, which renders these cells more susceptible toward additional PRMT5 inhibition compared to MTAP-competent cells." (PMID 33123121, 2020). "We illustrated that PRMT5 expression was positively correlated with tumor stages, lymphatic metastasis, and unfavorable outcome." (PMID 33060569, 2020). "This enhances the dependence of the tumor cells for PRMT5 and studies have demonstrated PRMT5 inhibitors show antitumor effects against GBM." (PMID 33312955, 2020). "In CRC, PRMT5 has been found to be overexpressed in approximately 75% of patient tumor samples, as well as being negatively correlated with patient survival." (PMID 32731506, 2020). "Increased abundance of infiltrated immune cells seen upon PRMT5 inhibition coincides with enhanced anti-tumor immunity." (PMID 32743345, 2020). "PRMT5 has been previously shown to be overexpressed in approximately 75% of CRC patient tumor samples, as well as negatively correlated with CRC patient survival." (PMID 32731506, 2020). "It is expressed at high levels in diverse tumours where it has been suggested to promote invasion and migration, observations consistent with the frequent up-regulation of PRMT5 expression in late stage disease." (PMID 32709847, 2020). "Through the control of these complimentary pathways PRMT5 limits immune cell recruitment and activation as well as tumor recognition, which defines tumor immune evasion." (PMID 32743345, 2020). "The expression of PRMT5 was positively correlated with tumor stages, lymphatic metastasis, and poor outcome." (PMID 33060569, 2020). "Further, PRMT5 and E2F1 regulate invasion and migration, and in human tumours we identified a coincidental expression between PRMT5, E2F1 and motility-related genes." (PMID 32709847, 2020). "While aberrant expression of PRMT5 favors transformation and tumor growth in a range of hematologic as well as solid and soft tissue neoplasms, the events causing PRMT5 deregulation during cellular transformation remain largely uncharacterized." (PMID 32555249, 2020). "PRMT5 performs many functions in the human body, can regulate the growth and transformation of cells and is correlated with various types of tumours." (PMID 30704408, 2019). "PRMT5 has been extensively characterized as an oncogene that epigenetically silences the expression of vital tumor suppressor genes." (PMID 30858358, 2019). "We evaluated the potential anti‐tumor effects of PRMT5 targeting in a preclinical study involving a TNBC patient‐derived xenograft model, selected for its high PRMT5 mRNA expression." (PMID 30957988, 2019). "We further confirmed the tumorigenic function of the PRMT5/NF-κB axis in vivo using xenograft tumor models." (PMID 30713476, 2018). "Histone methylation by PRMT5 is critical to epigenetic regulation of gene transcription and modulates expression of gene targets such as cyclin E1, the Rb tumor suppressor and ribosomal proteins." (PMID 29518110, 2018). "While the broad activity offers an opportunity to test PRMT5 inhibitors in many tumour types, it also presents a challenge to identify patient populations that are most likely to benefit from PRMT5 inhibitor treatment." (PMID 29946150, 2018).
tumor (continued). "Previous studies demonstrated that PRMT5 plays an important role in the regulation of splicing in normal tissues and tumour models." (PMID 29946150, 2018). "Our proliferation data highlight that PRMT5 inhibition attenuates proliferation of many cell lines/tumour types and induces apoptosis in a subset of models." (PMID 29946150, 2018). "Nuclear PRMT5 expression was significantly higher in tumor samples from patients that smoked > 10 pack-years and inversely correlated with p16 status." (PMID 28107179, 2017). "Our findings are clinically significant, as PRMT5 depletion within established tumor xenografts or treatment of patient-derived BCSCs with a pre-clinical PRMT5 inhibitor substantially reduces BCSC numbers." (PMID 29262329, 2017). "We therefore engineered MCF7 cells to express a doxycycline (dox)-regulated PRMT5 silencing construct (Tet-ON-shPRMT5) in combination with constitutive expression of the luciferase gene enabling in vivo imaging of tumor growth." (PMID 29262329, 2017). "In summary, we have identified the significant role of PRMT5 as a tumor promoter in PDAC and CRC, as well as highlighted its potential to be exploited as an important therapeutic target." (PMID 28591716, 2017). "Significantly, treatment of BCSCs isolated from patient-derived tumors with a pre-clinical PRMT5 small-molecule inhibitor substantially reduced tumor-initiating potential." (PMID 29262329, 2017). "Our results suggest the tumor suppressor role of MP via inhibition of PRMT5 thereby regulating gene expression through histone arginine dimethylation." (PMID 28074910, 2017). "Consistent with a reduction in stem cells, we observed that PRMT5-depleted tumors were less proliferative, as indicated by differences in final tumor weight, BrdU incorporation, and tumor growth rate." (PMID 29262329, 2017). "The transcriptional repressor function of PRMT5 is also critical for the tumor cell release from the primary tumor through the epithelial-mesenchymal transition (EMT) and tumor metastasis." (PMID 28107179, 2017). "Though many mechanisms of the tumor-promoting tendencies of PRMT5 are still unclear, the insights provided by this study are extremely valuable in understanding the workings of PRMT5." (PMID 28591716, 2017). "Nuclear PRMT5 expression was inversely correlated with p16-status (p < 0.001) and was significantly higher in tumor samples from patients who smoked > 10 pack-years (p = 0.013)." (PMID 28107179, 2017). "Since PRMT5 is essential for tumor cell cycle and proliferation, we investigated the role of PRMT5 in HCC cell cycle regulation by flow cytometry." (PMID 27708221, 2016). "PRMT5 has been considered as a potential target for cancer due to its function in tumor cell cycle regulation." (PMID 27708221, 2016). "The statistical analysis of clinicopathological parameters showed a correlation between CDK4 and PRMT5 co-expression level and tumor size or tumor stage (P < 0.05)." (PMID 27708221, 2016). "Tumor cells need massive glucose uptake, and previous studies have shown that PRMT5 stimulates hepatic glucose metabolism." (PMID 27708221, 2016). "By statistical analysis of clinicopathological parameters of these 75 HCC patients, PRMT5 protein levels were observably correlated with HCC tumor stage (P = 0.029)." (PMID 27708221, 2016). "On the basis of these findings, we propose a model for the function of PRMT5 specific siRNA or inhibitor AMI-1 in tumor growth." (PMID 26078354, 2015). "Taken together, our results point to a critical role for aberrant KLF4 regulation by PRMT5 in genome stability and breast carcinogenesis." (PMID 26420673, 2015). "Of the 48 tumor samples, PRMT5 expression was elevated significantly in 36 (75%) CRC tissues compared to the corresponding normal adjacent tissues (NATs)." (PMID 26078354, 2015). "With regard to PRMT5 it has been reported that a knock-down of this methyl transferase restored the sensitivity of several tumour cell lines to TRAIL-induced cell death." (PMID 26373535, 2015).
tumor (continued). "On day 7 after xenograt implantation, mice carrying palpable subcutaneous SW480 tumor xenografts received intratumorally (i.t.)or intravenously (i.v.)injections of formulated si-PRMT5." (PMID 26078354, 2015). "PRMT5 has been found to be overexpressed in multiple tumor types, including leukemia, lymphoma, lung cancer, colorectal cancer and breast cancer." (PMID 26541651, 2015). "In this study, we demonstrate that AMI-1 is able to inhibit PRMT5 activity in human CRC tumor tissues." (PMID 26078354, 2015). "Here, it has been reported that a knock-down of PRMT5 restored the sensitivity of several tumour cell lines to TRAIL-induced cell death." (PMID 26373535, 2015). "Most of the cells within resected tumors showed diffuse cytoplasmic PRMT5 while the number of PRMT5 expressing nuclei varied within a tumor." (PMID 24326178, 2013). "Loss of the MTAP gene increases the dependence of MTAP‐deleted tumours on PRMT5." (PMID 41537447, 2026). "First‐generation PRMT5 inhibitors such as GSK3326595 do not distinguish normal cells from MTAP‐deficient tumour cells." (PMID 41537447, 2026). "In tumours with loss of methylthioadenosine phosphorylase (MTAP), inhibition of methionine adenosyltransferase 2α (MAT2A) or protein arginine methyltransferase 5 (PRMT5) also induces a synthetic lethal effect." (PMID 41537447, 2026). "As noted, inhibitors targeting PRMT5‐MTA exhibit SL in MTAP‐deleted tumours." (PMID 41537447, 2026). "In the PRMT5-knockdown alone model, PRMT5 knockdown tumor cells secrete high levels of CXCL10." (PMID 41463372, 2025). "Given its dual role in oncogenic transcription and DDR regulation, targeting PRMT5 in MCC may simultaneously inhibit tumor growth and enhance sensitivity to DDR-targeting agents." (PMID 40846633, 2025). "However, the combination treatment reduced tumor growth significantly, indicating that PRMT5 inhibition in combination with carboplatin resulted in synergistic growth inhibition of chemo-resistant human tumors in vivo." (PMID 40091834, 2025). "Therefore, we provide a crucial missing link in understanding how PRMT5 inhibition leads from the initial T cell homing to its subsequent antitumor activity, thereby forming an immune “hot” tumor microenvironment." (PMID 41463372, 2025). "We speculate that the therapeutic index of MTA-cooperative PRMT5 inhibitors might ultimately be defined by the difference in MTA concentrations between tumor and normal tissues." (PMID 40377999, 2025). "Since we had established that PRMT5-mediated H4R3me2s mark is sufficient to regulate TCF3 splicing which subsequently regulates tumor cell invasion, we asked if targeting dCAS9-PRMT5 to the TCF3 splicing locus will be sufficient to enhance invasion by altering TCF3 splicing event." (PMID 41150697, 2025). "Disruption of PRMT5 was found to increase the secretion of chemokine CXCL10 by tumor cells." (PMID 41463372, 2025). "Additionally, the Gem-treated PRMT5 KO tumors exhibited a 30% reduction in tumor volume compared to the Gem-treated WT tumors (404.9 mm3 vs. 579.1 mm3, p = 0.046)." (PMID 40723820, 2025). "The tumor weights obtained at necropsy demonstrated similar trends in PRMT5 KO efficacy." (PMID 40723820, 2025). "PRMT5 inhibition enhances CPT‐11 sensitivity, inducing a PMS2‐deficient‐like state and cytosolic dsDNA release, which activates the cGAS‐STING pathway to promote anti‐tumor immunity." (PMID 40344511, 2025). "We wanted to confirm whether PRMT5 protein levels are also high in chemo-naive HGSOC tumors and whether PRMT5 levels change during tumor recurrence and chemoresistance." (PMID 40091834, 2025). "Moreover, the combination of a PRMT5 inhibitor with GSK3368715 produced a synergistic tumor growth inhibition effect." (PMID 39885614, 2025).
tumor (continued). "Here we show that monotherapy with selective PRMT5 inhibitors induced a potent anti-tumor activity across several cellular and animal models of ACC, which was paralleled by downregulation of genes associated with ACC tumorigenesis, including MYB and MYC (the recognized drivers of ACC progression)." (PMID 39794830, 2025). "Dysregulation of PRMT5 may significantly impact the migration of T cells that are present in the tumor microenvironment." (PMID 41463372, 2025). "As PRT543 was generally well tolerated by patients with recurrent/metastatic ACC, the anti-tumor activity of PRMT5 inhibitors may be further enhanced when given in combination with other therapeutic agents." (PMID 39794830, 2025). "Consequently, PRT382, a selective PRMT5 inhibitor, was developed, offering improved tolerance and anti-tumor activity." (PMID 39885614, 2025). "Downregulating PRMT5 or inhibiting its activity can specifically disrupt the intron-removal process during mRNA precursor processing, leading to the degradation of genes related to the cell cycle and proliferation and thereby counteracting tumor growth." (PMID 40450009, 2025). "In addition, PRMT5 contributes to the inactivation of the Hippo signaling axis, a tumor suppressor pathway." (PMID 40164592, 2025). "After identifying that the ERK1/2 and PI3K pathway proteins have an expressional correlation with PRMT5 in colon and rectum patient tumor samples, we next used the STRING database to determine which of the ERK1/2 and PI3K pathway proteins have demonstrated interactions with PRMT5." (PMID 41226455, 2025). "In the orthotopic tumor implantation model, we first titrated the combination of Gem plus Ptx to find the ideal dose that would allow us to assess the combination plus the PRMT5 inhibitor (PRMT5i)." (PMID 40723820, 2025). "As such, we first used the GEPIA database to analyze colon and rectum patient tumor gene expression data to determine whether the ERK1/2 and PI3K pathway proteins have an expressional correlation with PRMT5 in colon and rectum patient tumor samples." (PMID 41226455, 2025). "Furthermore, the increase in apoptosis upon PRMT5 depletion indicated that it also contributes to tumor cell survival." (PMID 41463372, 2025). "We also observed a significant positive correlation between PRMT5 and CA9 fluorescent staining indicating that PRMT5 is upregulated under hypoxia suggesting that PRMT5 upregulation is clinically relevant and can have implications in governing tumor progression." (PMID 41150697, 2025). "For example, dual targeting of PRMT1 and PRMT5 has produced synergistic inhibition of tumor growth." (PMID 40791817, 2025). "In the study described here, we investigated whether PRMT5 provides a target for tumor radiosensitization." (PMID 39068290, 2024). "Moreover, PRMT5 is consider as an oncogene in the context of its ability to repress expression of some tumor suppressor genes and regulate signaling molecules at a post-translational level." (PMID 39068290, 2024). "In other words, MTAP deletion sensitizes tumor cells to PRMT5 inhibition." (PMID 39711357, 2024). "Due to the complexity of the tumor environment in vivo, the anti‐tumor effects of PRMT5/MTA‐specific inhibitors may be somewhat attenuated, and their ability to achieve suitable therapeutic effects in the clinic might require more in‐depth studies." (PMID 39711357, 2024). "However, the primary application of PRMT5 inhibitors remains focused on anti-tumor therapies at this time." (PMID 39678513, 2024). "We identify a novel vulnerability in ATL resulting from the relationship of the synthetic lethality between the loss of NDRG2 expression and cytoplasmic PRMT5/MEP50 activity and reveal a functional and promising therapeutic target for the treatment of NDRG2low tumours." (PMID 38474089, 2024).
tumor (continued). "Our research provides evidence that except anti-tumor effect, PRMT5 inhibitor may also be applied to the treatment of various diseases related to ICs, such as chronic pain, dysgeusia, disorders affecting nervous system, muscles, heart, kidneys and so on." (PMID 39678513, 2024). "This suggests that combining a PRMT5 inhibitor with existing chemotherapies may prevent tumor progression." (PMID 38827324, 2024). "Some PRMT5 inhibitors were verified for anti-tumour effects in HTLV-1-transformed T cells." (PMID 38474089, 2024). "However, the reduced arginine methylation of E2F-1 by PRMT5 in tumor cells stabilizes E2F-1, subsequently leading to apoptosis and tumorigenesis." (PMID 38911125, 2024). "Our results may provide a concept of PRMT5-targeting molecules for anti-tumour activity in NDRG2low tumour cells." (PMID 38474089, 2024). "Therefore, in the MTAP deleted tumors, PRMT5 is a preferred molecular target for therapeutic development, because its inhibition appears to be more lethal than in tumor cells harboring the wild type MTAP gene." (PMID 38612768, 2024). "These demonstrated that arginine methylation of HSP90 through the phosphorylation of PRMT5 in the cytoplasm plays an important role in tumour progression and may represent a therapeutic target." (PMID 38474089, 2024). "PRMT5 promotes tumor metastasis by methylation-activated AKT." (PMID 39130639, 2024). "In addition, certain tumor suppressors, such as the metastasis suppressor Nm23, can be epigenetically silenced by PRMT5." (PMID 39424627, 2024). "Having identified MTAP‐WT cells' presence inside MTAP‐deleted tumors, we sought to investigate whether the PRMT5/MTA composition inhibitor played an ideal role in the tumor environment." (PMID 39711357, 2024). "We found that overexpression of UBR7 could effectively reduce the size of tumors, while the tumor after simultaneous overexpression of PRMT5 weight was larger." (PMID 39424627, 2024). "Thus, our findings suggest that PRMT5 recruits to the PD-L1 promoter and mediates PD-L1 expression through H3K4me3, thereby influencing tumor immunity in BC." (PMID 39366935, 2024). "Building on this knowledge, we investigated whether circGSK3β influences tumor immunity by modulating PD-L1 expression through PRMT5." (PMID 39366935, 2024). "Furthermore, methylation of STAT3 at arginine 609 by PRMT5 is important for its transcriptional activity and support of tumour growth and CSC maintenance." (PMID 38760429, 2024). "Finally, PRMT5 inhibition in vivo enhanced the radiation-induced growth delay of two types of subcutaneous tumor xenografts." (PMID 39068290, 2024). "Thus, based on this knockdown approach, PRMT5 can serve as a determinant of tumor cell radiosensitivity." (PMID 39068290, 2024). "Correlation analyses of clinical characteristics indicated that patients with advanced N and M stages exhibited higher levels of PRMT5 expression, implying that PRMT5 may promote tumor cell metastasis and facilitate cell migration." (PMID 39678513, 2024). "Furthermore, the enhanced expression of NDRG2 remarkably inhibited the suppression of cell proliferation and the protein degradation of AKT and NEMO with the treatment of PRMT5 inhibitors in tumour cells." (PMID 38474089, 2024). "In lung tumors, the PRMT5-driven arginine methylation of the N-terminal tails of histones H3 and H4 can modulate chromatin structure to induce transcriptional silencing of regulatory and tumor suppressor genes." (PMID 39337530, 2024). "Notably, PRMT5 has been conformed to engage in the progression of LC and has a significant impact on the regulation of tumor characteristics." (PMID 39678513, 2024). "Furthermore, PRMT5 overexpression correlates with histological grade in multiple tumour types, including glioma." (PMID 38172189, 2024). "MAT2A depletion led to impaired tumor growth and PRMT5 activity in MTAP-deleted cells." (PMID 37091983, 2023). "Genetic knockout of PRMT5 robustly inhibited tumor growth in vivo." (PMID 36797243, 2023).